IL6 (interleukin 6)
Diseases named in the same sentence as IL6 in open-access papers (continued):
Sharing a sentence is not in itself a finding about the gene and the disease.
lymphopenia (384 papers, 2011 to 2026). Reduction in the number of lymphocytes. "Serial trends in viral antigen, CRP and IL-6, provide support that new or persistent lymphopenia is associated with ongoing viral replication and inflammation." (PMID 39810077, 2025). "When compared to those with no lymphopenia, symptom duration < 5 days, NIV/HFNC, eGFR < 60, higher N-Ag quanterix, and IL-6 > 5.8 were associated with new lymphopenia." (PMID 39810077, 2025). "A systematic review published in October 2020 revealed that hypoalbuminemia, lymphopenia, leukocytosis, elevated levels of interleukin 6, and prolonged PT time were found to be associated with mortality in children." (PMID 38130842, 2023). "TNF-α and IL-6 levels in the serum have been found to be strongly linked with lymphopenia, whereas levels in the serum of healed patients are nearly normal." (PMID 37767093, 2023). "Findings that increased IL-6 levels are associated with lymphopenia: a larger viral load, hypoxemia, systemic inflammation, and a worse prognosis lend credence to the important involvement of IL-6 in the pathogenesis of SARS-CoV-2 infection." (PMID 36851766, 2023). "Those levels also positively correlated with lymphopenia and the pro-inflammatory factors interleukin1β (IL1β), IL6, and C-reactive protein, markers associated with the anti-viral inflammatory response." (PMID 38313435, 2023). "The virus causes lymphopenia by stimulating immune cells such as macrophages to create two highly inflammatory cytokines, IL-1 and IL-6." (PMID 36298501, 2022). "A sustained inflammatory response driven by a ‘cytokine storm’, including the release of pro-inflammatory cytokines (TNF-α, IL-6, IL-8 and IL-10) and lymphopenia, is thought to be a major cause of life-threatening complications in SARS-CoV-2 patients." (PMID 36313994, 2022). "Since the beginning of the pandemic leukocytosis, lymphopenia and high levels of IL-6 have been consistently associated with poor prognosis in patients with COVID-19 infection." (PMID 33819261, 2021). "As previously reported, age, lymphopenia, and biochemical parameters such as D-dimer, IL-6, and ferritin were associated with disease severity." (PMID 34021148, 2021). "Lymphopenia has been associated with high levels of IL-6, IL-10 or tumor necrosis factor; IL-6 seeming to play a paramount role." (PMID 34630377, 2021). "Alternatively, virus can trigger inflammatory response in the form of SIRS, lymphopenia, macrophage activation and cytokine storm releasing IL-6, IL-10 and TNF-α which can cause myocarditis." (PMID 33615872, 2021). "While raised leucocyte count, lymphopenia, hypoalbuminemia, raised serum ferritin and raised IL-6 were found to be significantly associated with mortality of patients." (PMID 34548976, 2021). "Other than interleukin-6, an expensive analysis, D-dimer, hypernatremia and lymphopenia, few other parameters have been described as associated with adverse outcomes." (PMID 34300311, 2021). "It was also reported that elevated serum levels of TNF‐α and IL‐6 were negatively correlated with the total T‐cell count in severe cases of COVID‐19, indicating the potential involvement of these cytokines in lymphopenia and T‐cell loss." (PMID 32935333, 2021). "Multivariate Cox analysis in this study indicated that age, lymphopenia, respiratory rate ≥ 30/min, and IL-6 were independent high-risk factors associated with poor prognosis." (PMID 33731184, 2021). "Most studies have declared that lymphopenia and increased levels of certain cytokines, such as IL‐6, have been closely associated with the disease severity." (PMID 34626490, 2021). "Univariate analysis of the data revealed significant associations of lymphopenia and elevated IL6 serum levels with mortality." (PMID 32259129, 2020). "To date, it seems to be associated with a combination of relative neutrophilia and lymphopenia and production of major inflammatory cytokines, such as interleukin-6 (IL-6)." (PMID 29570259, 2019).
lymphopenia (continued). "Further, our data suggest that IL-6–induced, apoptosis-independent lymphocyte death was associated with lymphopenia in MCMV-infected Ifitm3–/– mice." (PMID 28240600, 2017). "Furthermore, our findings show that lower IGFBP-3 levels are associated with elevated IL-6 concentrations and more severe lymphocytopenia, suggesting a possible synergistic role of IGFBP-3 and IL-6 in exacerbating immune suppression." (PMID 40724799, 2025). "Moreover, we further observed that lymphopenia was associated with a lower level of IL-1β and a higher level of IL-6 in diseases with poor outcomes, potentially via a direct effect of cytokines on T-cell exhaustion." (PMID 37035158, 2023). "This refers to an increase in pro-inflammatory cytokines such as TNFα and IL-6 which might have a role in lymphopenia caused by T cell apoptosis." (PMID 37484181, 2023). "Type II IFN activation and cytokine responses (mainly IL-6 and IL-10) may cause a cytokine storm in some patients with a more severe acute phase of the disease, lymphopenia and multisystemic organ involvement." (PMID 36263058, 2022). "IFN-γ activation and cytokine responses (mainly IL-6 and IL-10) may cause a cytokine storm in some patients with a more severe acute phase of disease and lymphopenia and multisystemic organ involvement." (PMID 36263058, 2022). "An elevated level of IL-6 is highly consistent in COVID-19 disease and lymphopenia may be associated with a high level of IL-617,18." (PMID 33654090, 2021). "Besides, the detection of high titer of IL-6 in the dead patient of H5N1 influenza outbreak in 1997 also depicted the role of IL-6 activation in causing lymphopenia." (PMID 33757410, 2021). "Lymphopenia and elevated neutrophil count suggest an alteration of lymphocyte function and are associated with elevated secretion of IL-6 and TNF-alpha, since these inflammatory markers contribute to lymphocyte apoptosis as well as decreased proliferation of lymphocytes." (PMID 34454452, 2021). "In this respect, corticosteroids, TNF-α-blockers, and IL-6-blockers should be preferably used over other immunosuppressive agents that may cause severe lymphopenia." (PMID 33207589, 2020). "Mechanistically, Treg depletion may be a component of lymphopenia caused by apoptosis or extravasation into inflamed tissue, but it also may be a consequence of a direct inhibitory effect of proinflammatory cytokines, such as IL-6, on Treg differentiation." (PMID 37809093, 2023). "Moreover, up-regulation of proapoptotic proteins (B-cell lymphoma-2 protein-BCL-2, C-X-C motif chemokine ligand 10- CXCL10, and C-C motif chemokine ligand 2- CCL2) as well as interleukin 6 (IL-6) were presented as molecular alterations associated with lymphopenia in patients with this infection." (PMID 37046564, 2023). "Quantitative alterations in the effectors of the immune system such as lymphopenia and increased levels of IL-6, together with possible qualitative alterations associated with the ageing of the immune system, could act synergistically, causing a more serious condition." (PMID 32802142, 2020). "In our cohort, more advanced AKI stages were associated with marked lymphopenia and significantly higher levels of inflammatory and coagulation markers, including D-dimer, ferritin, CRP, procalcitonin, and IL-6." (PMID 41598421, 2026). "Lymphopenia and elevated levels of D-dimer, ferritin, IL-6, CRP, and procalcitonin were significantly higher in patients with stage 3 AKI than in patients with other AKI stages and the non-AKI group." (PMID 41598421, 2026). "Laboratory results indicated elevated levels of C-reactive protein (121.1 mg/L), creatinine (111 μmol/L), total bilirubin (22.8 μmol/L), interleukin-6 (26.2 pg/mL), and mild lymphopenia (280 cells/μL)." (PMID 40430794, 2025). "Association of higher oxygen requirements and lower eGFR with new or persistent lymphopenia suggest correlation to organ dysfunction, while higher IL-6 and higher viral load suggest an ineffective immunologic response." (PMID 39810077, 2025).
lymphopenia (continued). "CBCs and cytokine/chemokine analyses revealed transient lymphopenia and monocytopenia (only F331 model) on day 7 and a significant fold-increase of IFNγ, IL-6, MCP-1, MIG, and MIP-2 in mice that received Reg-1 KO B7-H3-CAR T cells." (PMID 40475601, 2025). "IL-6, in particular, has been shown in vitro to induce T cell death and interestingly was elevated in our cohort among those with persistent and new lymphopenia." (PMID 39810077, 2025). "By preventing cytokine storms and re-establishing immunological homeostasis, tocilizumab—an IL-6 inhibitor—enhances this strategy, especially for patients with lymphopenia." (PMID 40497938, 2025). "increased CRP, erythrocyte sedimentation rate (ESR) and interleukin 6 (IL-6), neutrophilic leukocytosis, lymphopenia and organ dysfunction are secondary to the systemic inflammatory state and/or a cytokine storm." (PMID 38702753, 2024). "Lymphopenia also appears to be inversely related to levels of IL-6 and therapeutically targeted IL-6 inhibition can lead to the correction of circulating lymphocyte counts." (PMID 40012912, 2024). "Together, these data demonstrate that RK is effective in ameliorating CAC by preventing severe lymphopenia and reducing IL‐6 blood concentrations in two different tumour models." (PMID 38302863, 2024). "Directly virus-induced pyroptosis, enhanced utilization by interleukin-6 (IL-6), and acute tissue sequestration seem to be the mechanisms of lymphopenia." (PMID 38304674, 2024). "On the contrary, patients from second wave had greater lymphopenia and IL-6 that those of first wave in India." (PMID 36817433, 2023). "Lymphopenia can be caused by direct viral infection since lymphocytes express Angiotensin-converting enzyme 2 (ACE2), cytokine storm with a significant increase of IL-6 induce lymphopenia and lymphocytic infiltration to organs." (PMID 37565145, 2023). "As generally acknowledged, mild/moderate, severe and critical patients show different levels of lymphopenia and IL-6 peak levels." (PMID 37656752, 2023). "Lymphopenia can result from various virus-related factors, including the occurrence of a cytokine storm characterized by elevated levels of the interleukin 6 (IL-6)." (PMID 37624800, 2023). "The results of the laboratory test showed severe lymphopenia (p < 0.021) and increased IL-6 levels (p < 0.004) in CAPA patients." (PMID 37359005, 2023). "In the present study, cytokine release syndrome was considered as IL-6 cutoff value higher than 40 pg/mL, accompanied by elevation of other markers of inflammation and lymphopenia." (PMID 36599875, 2023). "Regarding the lymphopenia and its correlation with IL-6 gene expression, IL-6 is known to upregulate the pro-apoptotic Fas, resulting in the loss of mature lymphocytes." (PMID 36674654, 2023). "Tocilizumab, an IL-6 receptor antagonist, treatment increased the number of circulating lymphocytes, further indicating that an increase in IL-6 is a major factor in the development of lymphopenia." (PMID 37767093, 2023). "IL-6, IL-10, and TNF-α seem to correlate with lymphopenia, while convalescent patients showed lower IL-6 and IL-10 levels, respectively." (PMID 36034704, 2022). "Additional MIS-associated abnormalities include leukopenia/lymphopenia, elevated serum D-dimer, PCT, creatine kinase, and IL-6." (PMID 35204599, 2022). "In this context, the highest predictive capacity corresponded to the combined analysis of IL-6 + FME + lymphopenia + creatinine." (PMID 35634332, 2022). "At the laboratory analysis lymphopenia, elevated erythrocyte sedimentation rate, C-reactive protein, lactate dehydrogenase, interleukin-6, serum ferritin, and D-dimer anomalies were found in all the patients." (PMID 36296214, 2022). "Interleukin-6 likely plays a central role in exercise-induced leukocytosis and late lymphopenia mediated by cortisol, as shown by IL-6 infusion in athletes." (PMID 36211340, 2022).
lymphopenia (continued). "When patients had both cancer and SARS-CoV-2, lymphopenia and decreased B lymphocytes becomes more pronounced, and IL-6 was also elevated." (PMID 36439504, 2022). "The patient had lymphopenia (lymphocyte count: 9%; reference range: 20–40%), decreased albumin level (3 gm/dl; reference range: 3.2–4.8 gm/dl) and increased IL-6 (27.26; reference range: 5–15 pg/ml) at the time of admission." (PMID 35044234, 2022). "That study also reported that high levels of blood IL-6, cardiac troponin-I, lactate dehydrogenase, and lymphopenia were observed more frequently in severe SARS-COV2." (PMID 35979974, 2022). "These persons all present lymphopenia, T cell exhaustion, and elevated level of inflammatory factors, such as interleukin-6 (IL-6)." (PMID 36123740, 2022). "During this period, more severe hematological abnormalities, such as lymphopenia, neutrophilia, neutropenia, and thrombocytopenia develop, and immunological parameters such as IL-6, CRP, and PCT, increase in severe cases." (PMID 35204599, 2022). "Lymphopenia, increased D-dimer, hypersensitive C-reactive protein (hsCRP), and interleukin-6 (IL-6) were elevated in them." (PMID 35103220, 2022). "The maximum predictive value corresponded to the combination of IL-6 + FME + lymphopenia + creatinine [AUROC 0.83 (0.75 -0.92), 86.27% sensitivity, 63.16% specificity, 76.4% accuracy, and OR 10.78 (3.83 - 30.32)]." (PMID 35634332, 2022). "The CRP remained elevated and interleukin-6 (IL-6) was 60.1 ng/mL (normal < 7 ng/mL); procalcitonin 0.19 μg/mL (normal < 0.5 μg/ml); while the elevated neutrophil count, lymphocytopenia and thrombocytopenia persisted." (PMID 35692034, 2022). "This hypercytokinemia, initially named “cytokine storm”, is associated with high levels of circulating tumor necrosis factor (TNF) and interleukin-6 (IL-6), profound peripheral blood lymphopenia and chemoattraction of mononuclear cells within the lungs." (PMID 34088975, 2021). "Higher-risk subgroups of COVID-19 patients tend to have lymphopenia accompanied by overall leucocytosis and high levels of inflammatory markers (C-reactive protein [CRP], fibrinogen, ferritin, IL-6)." (PMID 33832474, 2021). "It has been reported that elevated d-dimer levels, IL-6, hs-troponin, lactate dehydrogenase and lymphopenia levels were commonly seen in severe Covid-19 illness." (PMID 33185365, 2021). "This was accompanied by a systemic inflammatory response characterized by granulocytosis, lymphopenia, and increased levels of serum-amyloid P and interleukin-6." (PMID 34992548, 2021). "The most common laboratory findings in COVID-19 patients are elevated CRP levels, decreased albumin levels, increased ESR, lymphopenia, eosinopenia, increased IL-6, and increased LDH." (PMID 34445855, 2021). "Our results further suggest that lymphopenia is tightly correlated with maximum IL-6 concentration and less dependent on the timing of IFN." (PMID 34260666, 2021). "Concentrations of pro-inflammatory cytokines such as IL-6 positively correlated to severity of disease and with lymphopenia." (PMID 33493185, 2021). "Cytokine storm is a phenomenon of excessive inflammatory reaction and has been associated with lymphopenia, with greater levels of inflammatory markers (TNF alpha and Interleukin 6 [IL-6]) causing more lymphocyte death." (PMID 34912430, 2021). "Elevated inflammatory markers (ie, ferritin, CRP, D-dimer, fibrinogen, LDH, interleukin 6 [IL-6]), transaminitis, and lymphopenia were observed in all patients." (PMID 34548669, 2021). "GDF-15 levels also correlated with interleukin-6, C-reactive protein, ferritin and D-dimer levels and with neutrophilia and lymphopenia." (PMID 34829345, 2021). "Serum C reactive protein (CRP), erythrocyte sedimentation rate (ESR), fibrinogen, D-dimer, ferritin, lactatedehydegenase (LDH), interleukin 6 (IL-6) are increased; lymphopenia, thrombocytopenia, hypoalbuminemia and hyponatremia can be detected." (PMID 34773697, 2021).
lymphopenia (continued). "The patients with severe disease were older and had high ferritin, D-dimer, C-reactive protein, troponin, interleukin-6 (IL-6) levels, and neutrophilia with lymphopenia at admission." (PMID 34440121, 2021). "Increased IL6, lymphopenia, elevated neutrophils lasted longer in the fatal casea, who also had decreased C3." (PMID 33664741, 2021). "A multivariable regression analysis showed that advanced age, comorbidities, dyspnea, lymphopenia, and elevated levels of Fbg, CTnI, IL-6, and serum ferritin were significant predictors of disease aggravation." (PMID 33850192, 2021). "This leads to defective antigen presentation and lymphopenia, which causes the defective function of lymphoid cells, whereas monocytes remain potent and keep producing TNF-α and IL-6." (PMID 33673529, 2021). "Hematopoietic alterations are characterized by lymphopenia, thrombocytopenia, thromboembolism, and increased plasma levels of inflammatory cytokines and chemokines (i.e., IL-6, CCL2, TNF-α)." (PMID 34944747, 2021). "Together, we find that many systemic clinical features — including cytokine production in MAS, specifically — require macrophage responsiveness to IFN-γ, while others, including IL-6 induction and lymphopenia, were unaltered." (PMID 34314387, 2021). "Biomarkers predicting severe disease include different markers of inflammation and acute phase reaction (e.g. CRP, procalcitonin (PCT), white blood cells (WBC), lymphopenia, interleukin 6 (IL-6))." (PMID 34324560, 2021). "Lymphopenia and elevated levels of neutrophil count, C-reactive protein, interleukin 6, D-dimer, creatinine, lactate dehydrogenase, cTnT, and NT-proBNP were more commonly seen in severe cases." (PMID 33092539, 2020). "From the little we know in the inflammatory response triggered by SARS-CoV-2, during this infection lymphopenia is observed, with loss of CD4 + and CD8 + T cells, hyperproduction of IL6, IL10, IL2R, TNFa and CCL2." (PMID 32883368, 2020). "In patients with severe respiratory failure and ARDS, immune dysregulation characterized by sustained TNF and IL-6 production and IL-6-mediated low HLA-DR expression as well as lymphopenia was reported." (PMID 33133083, 2020). "Critically ill patients usually develop neutrophilia, lymphopenia and strikingly elevated levels of IL-6." (PMID 32681497, 2020). "Elevated CRP, ALT, neutrophil, urea, decrease albumin, lymphopenia, and IL-6 were also observed in worsening cases resulting in mortality, indicating progression into critically level with resulting liver and renal function test derangement." (PMID 33456651, 2020). "This is also observed in SAVI syndromes (induced by gain of function of STING), where over-activation of STING by viruses can lead to T cell hyper-responsiveness with IL-6 secretion (as well as T cell exhaustion, and autophagy-induced lymphopenia)." (PMID 33335532, 2020). "Both lymphopenia and T cell exhaustion were directly correlated with the increase in the levels of IL-6, IL-10, and TNF alpha and with disease severity." (PMID 33072103, 2020). "For example, peripheral interconversion between Th17 cells and Tregs has been observed in the presence of IL-6 and TGF-β1, and a loss of Foxp3 expression along with regulatory functions has been observed in the context of lymphopenia." (PMID 33289628, 2020). "Compared with severe and moderate patients, lymphocytopenia occurred in 85.71% critically ill patients, and serum IL-2R, IL-6, IL-8, TNF-α, LDH, and cTnI were also increased in 71.42%, 83.33%, 57.14%, 71.43%, 100% and 42.86% in critically ill patients." (PMID 32788884, 2020). "We saw an increase in IL-6 and improvements in both lymphopenia and oxygenation as measured by PaO2/FiO2." (PMID 33353546, 2020). "Parallels seen in late-stage disease mice include: high viral loads (RNAemia), elevated AST and ALT, elevated neutrophils, lymphopenia, and increases in IL-10, IL-6, IFN-γ, CCL2, CCL5, and TNF-α." (PMID 31790513, 2019).